SNORD68 (small nucleolar RNA, C/D box 68)
Synonyms: HBII-202
Gene: Small nucleolar RNA gene on chromosome 16 (89,561,434 to 89,561,517, forward strand). Ensembl gene ENSG00000200084.
Gene Ontology:
Biological process: RNA processing
Cellular component: nucleolus
Homologues: Orthologues: chimpanzee SNORD68 (99% identical), macaque SNORD68 (92% identical), mouse Snord68 (86% identical), rat LOC120098677 (86% identical), guinea pig SNORD68 (81% identical), rat LOC120097582 (81% identical), rabbit SNORD68 (74% identical).